CD36 (CD36 molecule (CD36 blood group))
Diseases named in the same sentence as CD36 in open-access papers (continued):
Sharing a sentence is not in itself a finding about the gene and the disease.
metabolic disorders (continued). "AGE also signal through the scavenger receptor CD36; the role of CD36 in metabolic disease is controversial, with some data demonstrating beneficial cellular and systemic metabolic effects, while other data demonstrate the opposite." (PMID 31875018, 2019). "More studies in European and other populations are needed to precise the role of CD36 in cardio-metabolic diseases." (PMID 31748580, 2019). "Prolonged sublethal microcystin exposure decreased the expression of SREBF1 mRNA in mice, which further decreased the expression of CD36 in thyroid dysfunction and metabolic disorders in mice." (PMID 30127774, 2018). "Given the increasing prevalence of metabolic defects associated with deregulated glucose and lipid metabolism and with mitochondria dysfunction, targeting CD36 with GHRPs appears to be a safe option for the treatment of metabolic disorders." (PMID 29883404, 2018). "Authors reported that salvianolic acid B (SAB), a polyphenol compound extracted from the roots of Salvia miltiorrhiza, is a CD36 antagonist that blocks the uptake of oxidised lipids in macrophages, making CD36 a potential target for intervention in metabolic disorders." (PMID 40565598, 2025). "CD36 deficiency under atherogenic conditions not only significantly alters the ATM dynamics, but also decreases adipocyte hypertrophy, which is associated with adipose tissue dysfunction and metabolic disease." (PMID 39156133, 2024). "Previous studies have examined the role of CD36 in renal disease, metabolic disease, and others." (PMID 38584832, 2024). "CD36 is correlated with the progression of metabolic diseases." (PMID 36979708, 2023). "CD36 plays an important role in metabolic disease in children." (PMID 40625574, 2023). "Given that the CD36 protein has multiple ligand‐binding regions, we speculate that sCD36 may also bind with corresponding ligands to play roles in metabolic diseases and even be involved in the cross‐talk between organs." (PMID 40625574, 2023). "Given the early pivotal role of CD36 in metabolic disease development, in particular when related to altered lipid metabolism, several investigators have started to apply CD36 as a target for metabolic intervention therapy in order to normalize cardiac metabolism and restore contractile function." (PMID 35125400, 2022). "Research has indicated that Artemisia plant extracts could prevent metabolic disorders induced by a high-fat diet in mice by downregulating the expression of CD36, TNF-α, IL-6, IFN-α and IFN-β genes in epididymal adipose tissue." (PMID 35625074, 2022). "Indeed, in recent years various studies have documented such role for CD36 in metabolic disease development." (PMID 35125400, 2022). "Although the important roles of CD36 on metabolic disorder-induced proximal tubulopathy has been emphasized in many studies, FFA transports in renal proximal tubular cells also involve fatty acid transport -1 & -2, and plasma membrane fatty acid binding protein." (PMID 34830289, 2021). "Experimental and clinical studies have fortified the noteworthiness of CD36 in metabolic disorders." (PMID 34360006, 2021). "The mechanistic role of CD36 in metabolic diseases is seemed to be complex and yet to be resolved." (PMID 34648514, 2021). "The transmembrane glycoprotein CD36, which is responsible of the metabolic disorders, and the elevated intake of fat induces lipid buildup, is a multifunctional scavenger receptor signaling those functions in high-affinity tissue uptake of long-chain fatty acids." (PMID 34853341, 2021). "Whether CD36 could serve as a useful biomarker for personalized medicine is not known, but with clinical trials targeting CD36 for patients with metabolic disease, an opportunity to repurpose an anti-CD36 molecule remains of interest." (PMID 34215227, 2021). "Notably, the modulation of Cd36-Pparg pathways provides attractive options for the treatment of metabolic diseases, where caspase-1 is also a potential target molecule." (PMID 34502478, 2021).
metabolic disorders (continued). "Hence, manipulating CD36 might be a feasible therapeutic strategy to regulating metabolic disorder in the failing heart." (PMID 40027179, 2025). "Furthermore, growth hormone-releasing peptides could function as ligands to target CD36 and lead to downstream activation of PPARγ in metabolic diseases." (PMID 34094645, 2021). "For example, a study demonstrated that remodeling of the ECM in adipose and muscle tissue plays a pivotal role in metabolic disease development, identifying genes such as TCF7L2, ADIPOQ, CD36, PPARG, IL6, SIRT1, and COL5A1 as key regulators of inflammation." (PMID 41303617, 2025). "It’s worth noticing that CD36 has been reported in several metabolic diseases, but there is currently no literature suggesting a relationship between CD36 and DPN." (PMID 37248406, 2023). "Our study suggests that the MGIG could be used to correct metabolic disorders that would benefit from the suppression of the levels of SREBP‐1c and its downstream targets, SCD1 and FAT (CD36)." (PMID 32410294, 2020). "CD36 and LOX-1 are important, since they have been associated with atherogenic and metabolic disease but not fat redistribution." (PMID 27525284, 2016). "PPARγ participates in mediating metabolic disorder via numerous downstream adipogenic and lipogenic genes, which are important for adipocyte maturation, lipid accumulation, and insulin-sensitive glucose transport, including FAS, ACC, aP2, SCD-1, and CD36." (PMID 23533476, 2013). "PPARs participate in mediating metabolic disorders via downstream genes which are important for adipocyte maturation, lipid accumulation, and insulin-sensitive glucose transport, including PGC1-α, PGC1-β, aP2, LPL, ACC, ACO, CD36, UCP-2 and Glut4." (PMID 24312343, 2013). "Considering the role of H4K16ac modification in promoting promoter activation by regulating nucleosome accessibility and its involvement in the epigenetic regulation of metabolic disorders, we hypothesized that H4K16ac modification might direct SLC9A6‐126aa to regulate CD36 transcription." (PMID 39107881, 2024). "For example, Cd36, a fatty acid translocase, promotes the uptake of FFAs and cholesterol under HFD conditions, which may contribute to the pathogenesis of NAFLD and its related metabolic disorders." (PMID 36071929, 2022).
cardiovascular disease (43 papers, 2009 to 2026). "Long-term follow-up is needed to definitively resolve the controversy over the association of the CD36 gene defect with cardiovascular disease." (PMID 37239003, 2023). "The cluster of differentiation 36 (CD36) is one of the main receptors implicated in the pathogenesis of the cardiovascular disease." (PMID 35396566, 2022). "Changes in CD36 levels/function have been implicated in the alteration of myocardial metabolism in the pathophysiology of certain cardiovascular diseases." (PMID 36292100, 2022). "CD36 has been associated with numerous cardiovascular traits in human including blood lipid levels, platelet count, and cardiovascular disease prevalence in human genetic studies." (PMID 31344026, 2019). "Circulating CD36 and oxLDL levels are associated with cardiovascular risk factors in young subjects and may be potential early markers for cardiovascular disease (CVD)." (PMID 24766787, 2014). "A large number of studies have revealed the importance of targeting vascular or endothelial cell CD36 in the treatment of vascular injury and cardiovascular disease." (PMID 39595632, 2024). "The percentage expression of CD36 on ASCs was lower in the presence of cardiovascular disease (30.0% versus 59.8%; p = 0.029), with a statistically significance level that would not survive adjustment of type I error inflation due to multiple testing." (PMID 36952215, 2023). "Although CD36 was already described as a progenitor of white adipose tissue, this is the first time that it was verified in patients with cardiovascular disease." (PMID 35455943, 2022). "As such, CD36 may serve as a target in restoring endothelial function to prevent the progress of cardiovascular disease by rescuing Kir2.1-mediated NO production." (PMID 38586877, 2024). "This suppresses protein CD36, preventing the uptake of oxidized low-density lipoprotein (ox-LDL) and cardiovascular diseases (CVDs)." (PMID 41226575, 2025). "We have extensively studied the role of CD36 in the development of cardiovascular disease and recently found that TSP1-TSR/CD36 signaling enhances VSMC proliferation." (PMID 39742002, 2024). "In this study, we focused on CD36 and glutathione (GSH), which are reported to participate in vascular remodeling under different pathological conditions of cardiovascular disease." (PMID 38196515, 2023). "The decreased adipose tissue correlates with a healthier blood lipid profile in Cyp51+/− females and decreased expression of Cd36 accounting for the protective effect from cardiovascular diseases in Cyp51+/females, but not in males." (PMID 25393872, 2014). "Lack of CD36 participation in aortic endothelial cell activation by oxidized PAPC further extends the divergence in signal mechanisms elicited by the same ligands in endothelial cells, platelets, and macrophages, representing different cell types with prominent roles in cardiovascular disease." (PMID 24400094, 2014).
bacterial infection (17 papers, 2013 to 2025). "Here, MCTRs reversed several transcriptional changes in pulmonary tissues post-IAV infection, including an increase in Cd36 and Marco expression and a decrease in several genes associated with host susceptibility to bacterial infections." (PMID 35913160, 2022). "SOD2 is a critical regulator of antiviral signaling, while CD36 is known to promote inflammatory responses and phagocytosis, processes involved in the host response to both viral and bacterial infections." (PMID 40355874, 2025). "A previous study showed that CD36 is required for free FA uptake by HSCs during acute bacterial infection and their cell cycle entering to provide a hematopoietic response." (PMID 39852359, 2025). "Similar to our findings, zebrafish CD36 (a family member of SCARB) was down-regulated in response to bacterial infection." (PMID 28886690, 2017). "Release of the pro-inflammatory LPS upon bacterial infection of the wounds may induce the expression of Dnmt1, which in turn upregulates the expression of CD36 and downregulates the expression of SOAT1 and ABCA1, probably by a DNA-methylation-based mechanism." (PMID 37291182, 2023). "However, there are few studies demonstrating the effect of TLR2 on CD36 expression upon bacterial infection." (PMID 24058538, 2013). "Not only do CD36−/− HSCs possess full regenerative potential, CD36−/− HSCs also produce a balanced myeloid-lymphoid graft, indicating that CD36-driven FFA uptake in HSCs is a specific response to LPS and bacterial infection." (PMID 35528134, 2022). "Without CD36-mediated FFA uptake, the HSCs are unable to enter the cell cycle, subsequently enhancing mortality in response to bacterial infection." (PMID 34880245, 2021).
kidney disease (16 papers, 2014 to 2024). "Studies have reported overexpression of CD36 and reduced β-oxidation, both associated with lipid droplet accumulation in the kidney, contributing to kidney disease." (PMID 39061837, 2024). "Platelet glycoprotein 4 (CD36), a scavenger receptor, is crucial to mediate lipid uptake and contributes significantly to mitochondrial damage in the context of kidney diseases." (PMID 39563263, 2024). "It was also reported that glycosylation of CD36 is crucial for its function in lipid metabolism and inflammatory signaling, significantly impacting the pathogenesis of kidney diseases." (PMID 39563263, 2024). "CD36 is significantly upregulated in kidney disease and can reflect the severity of tissue injury in kidney disease to some extent." (PMID 36876728, 2023). "The blocking of CD36-governed cellular processes is a promising strategy for treating obesity-related nephropathy." (PMID 32382547, 2020). "Recent studies have shown that renal abnormalities are attenuated in CD36−/− mice, suggesting that CD36 plays an important role in the pathogenesis of kidney diseases." (PMID 32382547, 2020). "The deletion of CD36 in mice largely reduced fatty acid uptake and ectopic renal lipid accumulation and prevented the progression of renal disease." (PMID 32382547, 2020). "Although it has been extensively studied in the context of kidney disease, the regulatory mechanisms of CD36 in pericytes during AKI-CKD progression remain unclear." (PMID 39563263, 2024). "Therefore, blocking the CD36-dependent pathway is expected to be a therapeutic strategy for a variety of kidney diseases, and novel CD36-targeting peptides have the ability of slowing the progression of CKD." (PMID 32382547, 2020). "In addition to acting as a fatty acid translocase, CD36 also functions as a novel mediator influencing binding and uptake of albumin in the proximal tubule, and CD36 is upregulated in proteinuric renal diseases." (PMID 30934807, 2019). "In kidney disease, a CD36 antagonist has been shown to prevent disease progression." (PMID 28821730, 2017). "Therefore, the involvement of SFN in CD36 requires future studies in the kidney diseases context." (PMID 36290577, 2022). "Thus, in this study, we hypothesized that CD36 expressed on synovial fibroblasts participates in cell adhesion, ECM deposition, and fibrosis and contributes to the development of FS since pathologic fibrosis in the shoulder capsule parallels that seen in equivalent liver, lung, and kidney disorders." (PMID 37593175, 2023).
heart disease (8 papers, 2009 to 2024). "The promoter region of CD36 contains PPARα response elements, and its expression levels during cardiac disease have been associated with levels of PPARα and PGC1α expression." (PMID 35050131, 2021). "Interestingly, the alterations in FAT/CD36 level or its function were linked with diminished fatty acid metabolism, elevated cardiovascular risk and heart diseases also in humans." (PMID 31040794, 2019). "Taken together, these data suggest that diminished CD36 activity in end-stage genetic heart disease contributes to reduced TG clearance by the failing myocardium." (PMID 24567073, 2014). "Increased expression of FAT/CD36, FATP1, UCP2 and UCP3 have all been implicated in development of lipotoxic heart disease." (PMID 19390571, 2009). "PCSK9 influences heart disease progression through multiple pathways, such as LDL receptor downregulation, which increases LDL levels, inflammation through engagement with Toll-like receptors (TLRs), and clot formation by interacting with platelet glycoprotein IV (CD36) to activate platelets." (PMID 39770423, 2024).
neurodegenerative disease (7 papers, 2019 to 2024). A disorder of the central nervous system characterized by gradual and progressive loss of neural tissue and neurologic function. "Both CD36 and TREM2 are understood to be neuroprotective; however, in pathological conditions like neuroinflammation, these have been associated with neurodegenerative diseases such as AD." (PMID 31352901, 2019). "Thus, the response of CD36 to different fatty acids is essential for the treatments against neurodegenerative diseases." (PMID 39619979, 2024). "However, CD36 protein is expressed in brain microglia, and interestingly CD36-mediated debris uptake regulates brain inflammation in neurodegenerative disease models." (PMID 36178190, 2022). "Suppressing the hyperactivation of microglia and astrocytes is an essential factor for slowing the progression of neurodegenerative diseases; thus, lower brain GFAP and CD36 concentrations may indicate suppressed neuroinflammation." (PMID 39619979, 2024).
inflammation (6 papers, 2016 to 2025). Aberrant reaction of the microcirculation characterized by movement of fluid and leukocytes from the blood into extravascular tissues. "Intestinal inflammation is associated with impaired lipid absorption, thus it is possible that increased SI Bifidobacterium acts to reduce SI inflammation and increase CD36 levels that ultimately increase lipid absorption." (PMID 37533066, 2023). "Conversely, loss-of-function of FTO inhibited palmitic acid-induced cardiac inflammation and altered CD36 expression by diminishing the stability of CD36 mRNA." (PMID 34881240, 2021). "To further verify the important role of CD36 in LHD anti-PA-induced cardiac inflammation, we transfected the exogenous CD36 plasmid into AC16 cells." (PMID 34881240, 2021). "Furthermore, they suppress NLPR3 inflammasome activation to reduce IL-1β and TGF-β/Smads signaling via CD36-mediated TLR4/6-IRAK4/1 signaling in animal and cell models, exhibiting the alleviation of fructose-induced cardiac inflammation and fibrosis." (PMID 27270216, 2016).
liver (5 papers, 2006 to 2024). "While the presence of CD36 exacerbates injury after acute transient middle cerebral artery occlusion (tMCAO) in the adult, in neonatal mice we observed much higher incidence of severe injury after acute tMCAO in mice that lack CD36." (PMID 35148760, 2022). "Decreased nuclear WTAP in NASH leads to the impairment of the WTAP/HDAC1 axis and increases the transcription of Igfbp1, Cd36 and Ccl2, which further increases lipolysis in WAT, hepatic FFA uptake and liver inflammation, respectively, finally causing NASH pathogenesis." (PMID 35927268, 2022).
immune disease (3 papers, 2010 to 2022). "Progranulin deficiency in mice is associated with deregulations of the scavenger receptor signaling of CD36/SCARB3 in immune disease models, and CD36 is a dominant receptor in taste bud cells in the tongue and contributes to the sensation of dietary fats." (PMID 34836380, 2021).
intestinal disease (3 papers, 2022 to 2025). "How CD36 influences the function of various intestinal cell types and the impact on intestinal disease pathogenesis should be further studied." (PMID 40502773, 2025).
gastrointestinal disorders (2 papers, 2021 to 2024). "Our findings in mice and biomedical databases support the contribution of CD36 variants to human gastrointestinal disorders." (PMID 34728772, 2021).
hematologic malignancies (2 papers, 2019 to 2025). "However, the precise roles of CD36 in hematologic malignancies, particularly the regulation of apoptosis and drug response, are still very limited." (PMID 31022903, 2019).
neurological diseases (2 papers, 2020 to 2022). "If the effect of CD36 on the actions of protein aggregates prove to be more common and involve other protein aggregates in addition to those of α-synuclein, the studies should extend to a broader range of neurological diseases." (PMID 35768560, 2022). "Targeting TSP1 or its signaling pathway including miR‐195 and CD36 may be a potential therapeutic strategy to slow down age‐dependent neurological diseases." (PMID 33029941, 2020).
psychiatric disorder (2 papers, 2021 to 2025). A disorder characterized by behavioral and/or psychological abnormalities, often accompanied by physical symptoms. "Our findings strengthen the potential of CD36 as a therapeutic target for modulating inflammasome-mediated pathways and the microbiome in psychiatric disorders." (PMID 33414380, 2021).
retinopathy (2 papers, 2015 to 2020). "We have previously shown that TSP-1 induction in oxygen-induced retinopathy participates EC apoptosis via CD36 and a similar mechanism might participate in EC apoptosis in BRVO." (PMID 26208283, 2015).